LAG3 (lymphocyte activating 3)
Diseases named in the same sentence as LAG3 in open-access papers (continued):
Sharing a sentence is not in itself a finding about the gene and the disease.
tumor (continued). "Although LAG-3 is often co-expressed with PD-1 on tumor-infiltrating lymphocytes, they are distinct immune checkpoint inhibitors that can be regulated and expressed independently." (PMID 38920700, 2024). "Gene expression analysis using the nCounter system showed higher expression of tumor immunity‐related genes, such as PD‐L1, LAG3, and IDO1, in PTCL‐TBX21 than in PTCL‐GATA3." (PMID 38234210, 2024). "In the TME, the activation of LAG-3 can enhance the function of Tregs and inhibit the clearance of tumor cells by the immune system, thereby promoting tumor immune escape." (PMID 39660130, 2024). "The coexpression of PD-1 and LAG-3 is observed in tumor-infiltrating lymphocytes and contributes to T-cell exhaustion; coinhibition of PD-1 and LAG-3 showed synergistic response in preclinical models." (PMID 38730700, 2024). "Tumor-specific OT-I T cells isolated from the tumors exhibited high levels of PD-1 and LAG3, whereas bystander P14 cells isolated from the same tumors displayed much lower levels of these markers." (PMID 38702343, 2024). "The upregulated genes in PTCL‐TBX21 included Th1‐related genes, including CXCR3, CD38, INFG, CXCL9, CXCL11, IL27, and genes associated with tumor immunity, such as CD274 (PD‐L1), LAG3, and IDO1." (PMID 38234210, 2024). "Tumor-infiltrating lymphocytes (TILs) expressing high levels of LAG-3 are usually dysfunctional, characterized by decreased proliferation and decreased ability to secrete cytokines such as IL-2, TNF-α and IFN-γ." (PMID 39660130, 2024). "In contrast, expression of LAG3 was upregulated in peri-tumor samples compared to CVH and ARLD groups (p = 0.02)." (PMID 39944754, 2024). "VV-scFv-TIGIT’s anti-tumor efficacy was explored alone and in concert with PD-1 or lymphocyte-activation gene 3 (LAG-3) blockades." (PMID 38558795, 2024). "Ultimately, it is necessary to investigate novel amalgamations of LAG-3 therapy, which have the potential to result in improved therapeutic strategies and curative interventions for diverse tumor types." (PMID 38390331, 2024). "Compared to MSS tumors, the tumor microenvironment of dMMR/MSI-H CRC shows a significant upregulation of immune checkpoints like PD-L1, CTLA-4, LAG-3, and IDO, which generate tumor-associated immunogenic antigens." (PMID 39839672, 2024). "YY1 is involved in tumor resistance to immune checkpoint inhibitors (ICIs) immunotherapy, achieved through the positive regulation of PD-1 and LAG-3." (PMID 39796650, 2024). "The other targeting strategy involves the blockade of immune checkpoint inhibitors (e.g., PD-1/PD-L1, CTLA-4, TIM-3, and LAG-3; see Section 5.2) to modulate the immune response towards tumor cells and increase the probability of tumor cell death." (PMID 38258110, 2024). "So far, most studies on LAG-3 have mainly emphasized its role in T-cell dysfunction and its negative regulatory role in tumor immune response." (PMID 39252941, 2024). "The integration of CPMV IIT with LAG-3 inhibition holds significant potential to improve treatment outcomes by concurrently inducing a comprehensive anti-tumor immune response, enhancing local immune activation, and mitigating T cell exhaustion." (PMID 38349406, 2024). "Through scRNA-seq analysis in human tumor samples, Lymphocyte-activation gene 3 (LAG3), T-cell Immunoglobulin and Mucin-domain containing-3 (TIM3), and T cell immunoreceptor with Ig and ITIM domains (TIGIT) were upregulated and co-expressed in CD8+ T-cells." (PMID 38649887, 2024). "While NK cells are affected by LAG3 inhibition, LAG3 is also expressed on adaptive tumor-infiltrating lymphocytes, such as T cells, which are known to significantly influence tumor dynamics." (PMID 39192980, 2024). "RO-7247669 is an innovative bispecific antibody developed by Roche that uniquely targets both LAG-3 and PD-1, two critical immune checkpoints involved in the regulation of anti-tumor immunity." (PMID 39743998, 2024).
tumor (continued). "Focusing on tumor microenvironment (TME), CTLA-4, PD-1, and LAG-3 are expressed by immune cells, whereas PD-L1 is expressed by tumor cells." (PMID 38927526, 2024). "We found that CTLA4 was highly expressed in tumor tissues and LAG3 was lowly expressed in tumor tissues." (PMID 38604154, 2024). "Another study reported that TILs expressed LAG-3, which plays a crucial role in the tumour microenvironment." (PMID 38660136, 2024). "The co-targeting of LAG-3 with other immune checkpoint inhibitors has shown substantial promise in augmenting anti-tumor immunity." (PMID 39743998, 2024). "PAD4 inhibitors are able to inhibit the expression of genes, such as PD1 and LAG3, which are potential immune checkpoint inhibitors, and their ability to inhibit tumor progression can be enhanced in combination with anti-CTLA-4 and anti-PD-1 antibodies." (PMID 38543229, 2024). "Immune checkpoint molecules (ICMs; PD‐1, PD‐L1, CTLA‐4, LAG3), tumor‐infiltrating lymphocytes (TILs; CD8, FOXP3), and other related proteins were evaluated by immunohistochemistry." (PMID 38455493, 2024). "On the other hand, interaction of LAG-3 with MHC-II activates several survival pathways within tumor cells, including MAPK/Erk and PI3K/Akt signaling pathways." (PMID 39660130, 2024). "In this study, increased expression levels of LAG-3 were detected on tumor-infiltrating hepatic CD8+ T and NK cells in MC38 tumor–bearing mice." (PMID 38973608, 2024). "Recent research has highlighted FGL1 as a ligand for the immune checkpoint LAG-3, showing that its interaction with LAG-3 on T cells induces T cell depletion, facilitating tumor immune evasion." (PMID 38816776, 2024). "By integrating LAG-3 inhibitors with these emerging therapies, researchers hope to address the multifaceted nature of tumor immune evasion." (PMID 39743998, 2024). "Several studies have reported that in the tumor microenvironment, LAG3 is expressed on the surface of TILs (CD4+ and CD8+ T cells), including Treg cells, B cells, NK cells, NKT cells, plasmacytoid DCs (pDCs), and tumor-associated macrophages (TAMs)." (PMID 38255322, 2024). "The observed correlations between YY1/LAG-3 expression and immune infiltration highlight their significant role in modulating the tumor microenvironment." (PMID 39796650, 2024). "LAG-3 and PD-1 synergistically regulate T cell functions, thereby attenuating anti-tumor immune responses." (PMID 38762484, 2024). "In untreated metastatic or inoperable melanoma patients, combination treatment of Relatlimab (an anti-LAG-3 monoclonal antibody) with nivolumab demonstrates anti-tumor activity, significantly improving patients’ progression-free survival." (PMID 38762484, 2024). "Analysis of genes related to TIME revealed no significant expression changes, except for the relative overexpression of LAG3 in tumor‐infiltrating immune cells and a relative decrease in IL21 expression." (PMID 39565059, 2024). "If an excessive deficiency of LAG-3 leads to the manifestation of various autoimmune phenomena, then an excessive expression of LAG-3 results in tumor immune evasion." (PMID 39331884, 2024). "Prior research has demonstrated that combined immunotherapy‐targeting anti‐PD‐1/anti‐LAG3 exerts a superior inhibitory effect on tumour growth in contrast to monotherapy." (PMID 38429900, 2024). "The first anti LAG-3 antibody for clinical use is Relatlimab which is able to reactivate T lymphocytes in tumor tissues in a significant way." (PMID 38322766, 2024). "MHC-II is a natural ligand for LAG-3, and their binding has an essential effect on the behavior of T cells and tumor cells." (PMID 39660130, 2024). "Anti-LAG-3 blockade monotherapy didn't demonstrate significant anti-tumor effects, and dual blockade of PD-1 and LAG-3 showed strong synergistic anti-tumor immune responses in preclinical studies." (PMID 38724599, 2024). "Among the new-generation of ICIs, lymphocyte activation gene 3 (LAG-3) serves as a crucial target for the development of tumor immunotherapies." (PMID 37841254, 2023).
tumor (continued). "In another animal study, tumor cells co-expressing PD-1/LAG-3 demonstrated more exhausted characteristics than positive TILsr-negative TILs alone." (PMID 38328405, 2023). "An increasing trend was noted also in the number of CD4+ T cells stained for TIM3 or LAG3 in tumor of SR59230A, αPD-L1 treatments and their combination, but they failed to reach statistical significance." (PMID 36854895, 2023). "Inhibitory ICPs like T-cell immunoglobulin mucin-domain containing-3 (TIM-3), programmed cell death protein-1 (PD-1), and lymphocyte activation gene 3 (LAG3), are all present on T-cells and bind to the ligands that are commonly produced by tumor cells." (PMID 36765348, 2023). "Among them, LAG-3 has been acclaimed as a new generation of tumor immunotherapy target after PD-1, with great application prospects." (PMID 37002211, 2023). "Here, we explored the potential use of the anti-LAG-3 antibody tracer [89Zr]Zr-BI 754111 as a predictive imaging biomarker and investigated its target specific uptake as well as the correlation of its tumor uptake and the tumor immune infiltration." (PMID 36859619, 2023). "The two cases in which LAG‐3 was diffusely expressed in the tumor cells were excluded from this analysis." (PMID 37326144, 2023). "Subgroup analysis based on tumor type indicated that higher expression of LAG3 was correlated with worse RFS in patients with ESCA (HR = 1.72, 95% CI 1.06–2.79, P = 0.028)." (PMID 38041068, 2023). "The results provided reliable evidence of a significant correlation between LAG3 and tumor immunity." (PMID 38041068, 2023). "The results indicate that the upregulation of LAG-3 in EBV (+) tumours is a result of an exhaustion expression programme triggered by EBV-associated activation." (PMID 37735150, 2023). "The upregulation of inhibitory pathways, such as PD-1 and LAG-3, synergistically contributes to autoantigen and tumour antigen tolerance, thereby resulting in severe exhaustion of CTLs." (PMID 37426674, 2023). "Engagement of LAG-3 by its ligands can contribute to the immune escape of tumor cells by mediating downstream signaling to affect T-cell immune activity." (PMID 37064147, 2023). "This suggests that when anti-PD-1, anti-CTLA-4 or anti-PD-1/anti-CTLA-4 in combination is used alone, tumor cells can develop immune resistance through compensatory upregulation of the immunosuppressive molecule LAG-3 and reduce the therapeutic effect." (PMID 38026944, 2023). "It has a higher affinity for PD-1 than for LAG3, which allows the bispecific antibody to target activated tumor-infiltrating T cells while effectively targeting Tregs." (PMID 37182149, 2023). "LAG-3 plays a negative regulatory role in tumor immunology by binding to its ligands, including the major class II tissue compatibility complex (MHC II)." (PMID 37895833, 2023). "Analyses of available pretreatment tumor biopsy samples reported that patients displaying higher baseline levels of LAG-3 expression by IHC tended to show improved response." (PMID 37857711, 2023). "The LAG-3 and PD-1 pathways are distinct inhibitory immune checkpoints that are often co-expressed on tumor-infiltrating lymphocytes." (PMID 38201531, 2023). "Elevated LAG-3 expression on tumor-infiltrating lymphocytes (TILs) has been found broadly in various solid tumor types, and has been significantly associated with unfavorable clinicopathological characteristics." (PMID 37795090, 2023). "Currently, four types of ICIs (anti-PD-1, PD-L1, CTLA-4, and LAG-3 mAbs) have been approved by the FDA for tumor treatment." (PMID 37670328, 2023). "Regarding clinical features, our results showed a relationship between high score of LAG3 in IM with tumor progression (higher T-stage and larger tumor size)." (PMID 36765348, 2023). "Expression of LAG-3, on the other hand, is well established as a marker of increased tumor progression and aggressiveness across cancer types." (PMID 38090565, 2023).
tumor (continued). "Subgroup analyses based on tumor type indicated that higher LAG3 expression was significantly correlated with worse survival outcomes in BLCA, CESE, ESCA, KIRC, LIHC, PAAD, SARC, and SKCM." (PMID 38041068, 2023). "In a subset of cases, high LAG-3 staining was observed only in focal ‘hotspot’ areas, with the remainder of the tumor showing apparent exclusion of LAG-3+ cells." (PMID 37808404, 2023). "As expected, in contrast to HPV mRNA-LNP vaccination alone or ICB alone, the combination of HPV mRNA-LNP vaccination and LAG3/CTLA4 blockade exacerbated synergistic effects on tumor growth." (PMID 37773254, 2023). "The cytotoxicity of Vδ2T cells against NSCLC tumor cell lines was enhanced after blocking PD-1, so the degranulation of γδT cells can be improved with the inhibition of the PD-1/PD-L1 or LAG-3 signaling pathway." (PMID 36793048, 2023). "In humans, LAG-3 is expressed on CD8+ tumour-infiltrating lymphocytes (TILs) and peripheral regulatory T cells (Tregs)." (PMID 36980527, 2023). "Within the EOC and TNBC cohorts, nearly all patients (20/21) with reduction in tumor lesions and evaluable tissue showed detectable levels of LAG-3." (PMID 37857711, 2023). "Checkpoint receptors on T and natural killer (NK) cells, including CTLA-4 and LAG-3, were highly expressed even in tumor-adjacent and normal tissues of liver, coincident with higher levels of B7-H3 and ARG1." (PMID 37768208, 2023). "As an inhibitory receptor, LAG3 exerts its influence on tumor progression by modulating T cell activation and effector function." (PMID 38115039, 2023). "Although there are currently no mAbs targeting FGL1, many mAbs targeting LAG-3 are undergoing clinical trials, including relatlimab (first LAG-3 mAb), and show good potential in tumor immunotherapy." (PMID 37872170, 2023). "Early clinical trials suggest that these more specialized immune checkpoints namely LAG-3 in combination with PD-1 blockade exhibit a superior safety profile compared with PD-1 plus CTLA-4 blockade with equivocal anti-tumor activity." (PMID 37520544, 2023). "The cytotoxic effects of CD8+ T cells on tumor cells are more direct, therefore we paid more attention to the influence of PD-1 and LAG-3 on the function of CD8+ T cells in the following experiment." (PMID 37841254, 2023). "Exposure to the tumor microenvironment induces sustained expression of LAG-3, resulting in alterations in cell proliferation and cytokine production." (PMID 38162657, 2023). "This review also examines emerging targets such as TIGIT and LAG3, the potential of antibodies in modulating the myeloid compartment, and tumor-specific targets for monoclonal antibody therapy." (PMID 37987252, 2023). "By blocking the FGL1/LAG3 interaction, antitumor immunity can be promoted by stimulating tumor-infiltrating lymphocyte activation and expansion in the TME36." (PMID 36765073, 2023). "Blockade of LAG-3 enhanced tumor-infiltrating T-cell responses in mismatch repair-proficient liver metastasis of CRC44." (PMID 37872170, 2023). "C5aR1 showed a negative correlation with the immunological status of TME and a positive correlation with most immune checkpoints in GC, including PD-L1, CTLA-4, LAG-3, and PD-1, which suppress the effector function of T cells and impede anti-tumor immunity." (PMID 36508191, 2023). "Due to its significant involvement in the formation of the tumor immunosuppressive microenvironment, LAG3 is anticipated to be correlated with an unfavorable prognosis in cancer patients." (PMID 38041068, 2023). "Immune checkpoint molecules (PD-1, PD-L1, PD-L2) and immune suppressor markers (Tim-3, FOXP3, LAG3) were all significantly expressed on tumor T-cells as well as co-stimulatory molecules (STING, B7-H3, OX40L, 4-1BB)." (PMID 38044986, 2023). "Another well-known cancer immune checkpoint, CTLA-4 also regulates anti-tumor immune responses to promote protective immunity and maintain tolerance, along with LAG-3." (PMID 37509517, 2023).
tumor (continued). "This dysregulated Tox expression acts to induce the immune checkpoint molecules (PD-1, TIGIT, LAG3) that suppresses T cell anti-viral/tumor activity and limits cytokine production." (PMID 38054003, 2023). "In this study, the expression of KIFC1 was positive with immune checkpoints like CTLA4, CD276, and LAG3 in most tumor types." (PMID 38112634, 2023). "Adoptive transfer of CD8+ T cells with edited PDIA3, MGA5, Emp1, or Lag3 improve the survival rate of GBM tumor-bearing mice in both syngeneic and T-cell receptor transgenic models." (PMID 37427373, 2023). "Herein, we primarily focused on four important immune checkpoints viz PD1, Tim3, CD38 and Lag3, which have frequently been reported to be expressed on tumor infiltrating T cells." (PMID 37566017, 2023). "Our findings generally suggest that the clinicopathological and prognostic significance of immune system-related markers such as CD45RO and LAG3 depends on the primary tumor sides." (PMID 36765348, 2023). "By integrating transcriptome data from TCGA and GTEx datasets, we further confirm the differential expression levels of LAG3 between tumor and normal tissues." (PMID 38115039, 2023). "In a second therapy experiment, we combined L19-mIFNγ KRG with a commercial anti-LAG3 antibody in the CT26 tumor model." (PMID 36839699, 2023). "Several reports suggest that LAG-3 works concomitantly with PD-1/PD-L1 to enhance tumor induced tolerance and mediate antitumor immunity." (PMID 37304291, 2023). "Our findings suggest that direct signaling between mesenchymal cancer cells and CD8+ T cells trigger LAG3 and other T cell exhaustion pathways, disrupting anti-tumor immunity and supporting tumor development." (PMID 38086828, 2023). "The combination of AU-011 with anti-LAG-3 and PD-L1 induced the strongest tumor growth inhibition and significantly enhanced survival, resulting in CR in approximately 75% of animals at 60 days post-inoculation." (PMID 36997666, 2023). "Immune checkpoint inhibitors have garnered substantial attention as a therapeutic strategy, with notable immune checkpoints, including CTLA4, PD-1, PD-L1, and LAG3, identified as effective targets for stimulating T cell-mediated anti-tumor immunity." (PMID 38162499, 2023). "An increasing number of studies have showed that various immune checkpoint receptors, such as PD-1, CTLA4, TIGIT, TIM3, LAG3, and inflammatory factors, are expressed and altered in the tumor microenvironment." (PMID 38110467, 2023). "The blockade of both LAG-3 and PD-1 augmented the proliferation and cytokine production of tumor-infiltrating CD8+ T cells after ex vivo stimulation with the tumor-associated antigen NY-ESO-1 in OC cells." (PMID 37670328, 2023). "Lymphocyte-activation gene 3 (LAG-3) is nearly always expressed in the tumor microenvironment of cHL and inhibitors of LAG-3 are now in clinical trials." (PMID 36937412, 2023). "LAG3 expression was evaluated in tumor center and invasive margin using immunohistochemistry and whole-slide digital image analysis." (PMID 37311986, 2023). "LAG-3 was most highly expressed by subsets of tumor-infiltrating CD8 T central memory (TCM) and effector memory (TEM) cells and was frequently co-expressed with PD-1." (PMID 37795090, 2023). "All animals bearing a single subcutaneous tumor that were treated with a single systemic dose of AU-011 combined with CTLA-4 or with PD-L1 together with LAG-3 antibodies had a CR." (PMID 36997666, 2023). "CSCs express CD47, CTLA4, PD-L1, TIM-3 and LAG3, which promote immune evasion in the malignant environment and maintain tumor survival." (PMID 36810098, 2023). "This discovery underscores the potential importance of LAG-3 as a promising checkpoint molecule for therapeutic strategies targeting EBV (+) tumours." (PMID 37735150, 2023). "Previous studies have provided evidence suggesting that LAG3 acts as an immune checkpoint, conferring immunosuppressive properties and facilitating tumor progression within the TME." (PMID 38041068, 2023).